INS (insulin)
Diseases named in the same sentence as INS in open-access papers (continued):
Sharing a sentence is not in itself a finding about the gene and the disease.
Obesity (continued). "Reducing dietary BCAAs rapidly reverses diet-induced obesity and improves glycemic control in obese mice, suggesting that reducing dietary BCAAs may be helpful in the treatment of obese and insulin-resistant patients." (PMID 36219347, 2022). "Furthermore, the more body fat a patient with obesity has, the higher the levels of different hormones such as estrogen and insulin, which are helpful to BMD by blocking bone resorption and boosting bone remodeling." (PMID 35651972, 2022). "Yet, the recent association between obesity and T1D supporting the “accelerator hypothesis” that the rising demand for insulin during obesity could lead to autoimmunity may position the ER stress as possible cause for immune cell infiltration." (PMID 36171907, 2022). "This study conducted on Asian Indian adults with overweight and obesity indicates that consuming 43 g of almonds daily as a snack over a period of 12 weeks results in improvement in insulin resistance and β cell function in addition to lowering of serum total cholesterol and body weight." (PMID 36704786, 2022). "Obesity affects insulin secretion, tissue sensitivity to insulin, and systemic inflammation, but this may not account for differences seen in the levels of vitamin D deficiency between the glycaemic groups, as BMIs were similar." (PMID 35956323, 2022). "There is increasing evidence for an association of plasma levels of taurine and the expression levels of its transporter with obesity and body mass index, indicating some role of this amino acid in body weight control, adipocyte biology, insulin secretion and glucose homeostasis." (PMID 35204736, 2022). "In obesity, lipid signals regulate insulin sensitivity, satiety, and pain sensation." (PMID 36042489, 2022). "Theoretically, increased leptin from obesity should cross the blood-brain barrier and suppress appetite at the neurochemical level but obese individuals are almost always leptin resistant much in the same manner that diabetics are insulin resistant." (PMID 36143948, 2022). "However, as with insulin, a resistance in ghrelin secretion has been reported among patients with obesity, resulting in lower ghrelin concentrations, while worsening glucose tolerance." (PMID 36011958, 2022). "Accordingly, changing the protein source from casein to a protein mix resembling a typical WD for human consumption altered the murine gut microbiota to enhance the generation of BCFAs exacerbating diet-induced obesity and hepatic insulin resistance through the mTORC1/S6K1 signaling pathway." (PMID 35291443, 2022). "Our results also give insight into how outcomes change with both obesity and insulin sensitivity." (PMID 35589784, 2022). "Among these, leptin, visfatin, and resistin have a pro-inflammatory role decreasing the insulin sensitivity and inducing the development of chronic complications; on the contrary, adiponectin shows anti-inflammatory properties in the context of obesity." (PMID 36386923, 2022). "Surprisingly, the decreased insulin tolerance via COX-2 deficiency was not pronounced despite a dramatic increase in body weight gain under 16 weeks of HFD feedings, implying a distinct effect of adipocyte COX-2 on insulin sensitivity in the early and late stages of obesity." (PMID 35681514, 2022). "In obesity, the IMAT secretome is highly immunogenic, secreting a distinct combination of cytokines, chemokines, adipokines and eicosanoids that are associated with insulin sensitivity." (PMID 35980018, 2022). "In addition, PLA2G5 knockout mice have hyperlipidaemia, increased obesity, hepatic steatosis, lower insulin sensitivity, greater infiltration of M1 macrophages, and a higher expression of proinflammatory cytokines." (PMID 36386829, 2022). "In obesity, chronic adipose inflammation is a crucial contributor to impaired insulin sensitivity." (PMID 36713454, 2022).
Obesity (continued). "Enlarged, hypertrophic adipocytes are less responsive to insulin and are a hallmark feature of obesity, contributing to many of the negative metabolic consequences of excess adipose tissue." (PMID 35163825, 2022). "Thus, the inability of selenite supplementation to enhance GPx3 in established obesity can explain why obesity prevents a supplemented Se-induced insulin-sensitizing effect in adipose tissue." (PMID 35624726, 2022). "Moreover, in obesity, excess adipose tissue becomes dysfunctional, promoting a pro-inflammatory, hyperlipidemic and insulin-resistant environment through the release of several inflammatory cytokines and chemokines." (PMID 35267956, 2022). "Finally, in 2019, the European Medical Agency approved sotagliflozin as adjuvant to insulin for T1D in adults, to be used in selected T1D patients with obesity and poorly controlled glycemia." (PMID 35745754, 2022). "More recently, new probiotic candidates, called next-generation probiotics, have been highlighted thanks to new technologies identifying specific alterations during obesity or through mechanistic studies establishing mechanisms of action beneficial for food intake regulation or insulin sensitivity." (PMID 35208906, 2022). "The original hypothesis that proposed decreased IRec binding was responsible for the typical obesity-related IR has given way to a concept where defects in insulin signaling via IRec play a major role in the development of IR." (PMID 35885586, 2022). "In addition, the elimination of ARTs in visceral fat enhanced insulin sensitivity during early-stage obesity and reduced the epididymal adipose tissue expression of T-cell-derived IFN-γ." (PMID 36552805, 2022). "In addition, it regulated the proteins related to adipogenesis and lipogenesis in 3T3-L1 adipocytes and HFD-induced obesity in mice, and the insulin regulatory pathway was confirmed in 3T3-L1 adipocytes." (PMID 35164174, 2022). "The disruption of the gut epithelial barrier precedes HFD-induced obesity in that compromised gut barrier allows higher uptake of bacterial endotoxins, which results in low-grade systemic inflammation (endotoxemia), eventually leading to insulin resistance." (PMID 36329549, 2022). "BBR and BRB similarly decreased Romboutsia, which was obesity-related bacteria, and Lactobacillus, which may decrease insulin sensitivity and increase inflammation." (PMID 35873595, 2022). "Lower hepatic fat content in Black South African women with obesity corresponded to higher hepatic insulin sensitivity compared with their White counterparts, as well as lower estimated rates of de novo lipogenesis, consistent with findings in African Americans." (PMID 36166072, 2022). "Furthermore, circulating CTRP9 levels are positively correlated with markers of obesity and IR, including BMI, fasting blood glucose level, insulin and LDL-C." (PMID 35370782, 2022). "Our results suggest that PC1/3 deficiency leads to obesity due to the absence of insulin-targeted anorexic pathways." (PMID 35963866, 2022). "A study showed that the gut microbiota tryptophan metabolite indole-3 carboxylic acid could regulate energy expenditure and insulin sensitivity by regulating the expression of miRNA-181 in white fat and thus affect obesity." (PMID 36245535, 2022). "Knowing the molecules that vary their expression due to the effect of these insulin-sensitizing molecules could help to better understand the failures observed in the endometria of women with obesity and PCOS." (PMID 35409282, 2022). "It is well-known that the increase of insulin and glucose in the bloodstream triggers systemic inflammation and oxidative stress, contributing to non-communicable chronic diseases’ impairment, such as T2D and obesity." (PMID 35326098, 2022).
Obesity (continued). "Due to the increasing worldwide prevalence of obesity and its undeniable relationship with decreased insulin sensitivity of the peripheral cells, there has been a growing interest in the study of proteins/peptides that may regulate metabolic homeostasis." (PMID 35206286, 2022). "Inflammatory cytokines and non-esterified fatty acids (NEFAs) are obesity-linked factors that disturb insulin secretion." (PMID 36138030, 2022). "However, humans with obesity have impaired insulin-stimulated muscle perfusion, which can compromise amino acid availability for protein synthesis in the muscle of these individuals." (PMID 35350688, 2022). "A central role for adipose ChREBPβ isoform in insulin sensitivity was suggested in different models of obesity and glucose intolerance where expression of ChREBPβ in white adipose tissue strongly correlates with lipogenic activity and systemic insulin sensitivity." (PMID 35041621, 2022). "During inflammation and obesity, autophagy is downregulated in macrophages, and macrophage-specific autophagy knockout mice have impaired insulin sensitivity in liver and adipose tissues when fed an HFD, inhibiting ROS in macrophages with antioxidants can restore insulin sensitivity of adipocytes." (PMID 36230963, 2022). "SCFA-GPR41 and GPR43 interactions trigger the expression of leptin from adipocytes and impact the inflammatory responses that are severe for the development of obesity-related metabolic disorders such as insulin resistance, lipogenesis, and increased triglyceride stores." (PMID 35448499, 2022). "Multiple factors may induce increased sympathetic activity in obesity: overfeeding-induced disruption of hypothalamic insulin-signaling, hyperinsulinemia, hyperleptinemia, and increased release of nonesterified fatty acids from adipose tissue." (PMID 36074318, 2022). "This was followed by a series of studies demonstrating that “β-cell rest” or acute inhibition of insulin secretion, could restore β-cell function (first phase insulin secretion), insulin/Ca2+ pulsatility, and insulin content in obesity and T2DM." (PMID 35355560, 2022). "However, it should also be noted that in an animal model that identified the metabolic outcomes of alcohol and cannabis co-exposure, the researchers observed a beneficial effect on obesity rates that was explained by improved glucose and insulin homeostasis." (PMID 35328862, 2022). "We also observed that obesity resulted in an increased complementary treatment with insulin." (PMID 35663318, 2022). "Our results suggest that adipocyte COX-2 partially mediates IF-induced Treg proliferation and improved AT inflammation and insulin sensitivity, which may be obesity independent." (PMID 35260536, 2022). "Strikingly, transgenic obesity- and diabetes-prone mice made to overexpress adiponectin in adipose tissue were found to develop extreme obesity but to retain a low size of individual adipocytes and remain insulin sensitive." (PMID 36172277, 2022). "Twelve weeks of treadmill training improved insulin sensitivity compared to the obesity group." (PMID 36615677, 2022). "Regardless, the placenta remains normosensitive to insulin in women with obesity, thus, increased placental insulin activation, along with leptin, has been shown to promote mTOR signaling leading to increased glucose and amino acid transport across the placental barrier and fetal overgrowth." (PMID 36329895, 2022). "Finally, clinical biochemistry demonstrates that, despite the extreme effect of severe obesity, cholesterol, triglycerides, and insulin metabolisms differ between men and women." (PMID 35629923, 2022). "As discussed in more detail below, CerS6-dependent C16:0 ceramide production is increased in specific tissues during obesity development, and transgenic expression of CerS6 in primary hepatocytes is sufficient to inhibit insulin-stimulated phosphorylation of AKT." (PMID 35789435, 2022).
Obesity (continued). "EPM301 not only modulated energy utilization, but also restored glucose and insulin homeostasis as well as reduced obesity-induced hepatic steatosis and liver injury, and normalized hyperlipidemia, an effect that is most likely modulated via affecting cellular hepatic LDL metabolism." (PMID 35628417, 2022). "Using CGM data from these two groups may offer insight into the plausibility of the Energy Balance model for obesity versus the Carbohydrate-Insulin model." (PMID 36570168, 2022). "In order to clarify a marked improvement in insulin sensitivity the same group of authors examined the effects of combined sacubitril/valsartan treatment on abdominal adipose tissue phenotype in hypertensive patients with obesity." (PMID 36419097, 2022). "Similarly, improved insulin sensitivity was observed in high-fat-diet-induced obesity mice by treatment with herring milt protein hydrolysate." (PMID 35409375, 2022). "Some studies have shown that ablation of p66Shc has protective effects against obesity and causes better insulin sensitivity; some reported that p66Shc-negative mice are leaner, but they are insulin resistant like wild-type mice." (PMID 36465704, 2022). "We observed an increase in serum total cholesterol, and fasting insulin levels in Batf3-/- mice as early as 8 weeks of age, which preceded the development of obesity, and increased fasting blood glucose levels in Batf3-/- mice compared to WT mice at 16 weeks of age." (PMID 35812447, 2022). "The same study reported vaspin to exert an insulin-sensitizing effect on WATs in states of obesity." (PMID 36289764, 2022). "Previous studies suggest that obesity-induced lymphatic damage may exacerbate metabolic abnormalities by increasing systemic and local inflammatory responses and regulating insulin sensitivity." (PMID 35885034, 2022). "Thus, while insulin signaling molecules expression are decreased in obesity, RYGB increases such expression." (PMID 36432612, 2022). "While there is much excitement surrounding the use of commercial CGM products in obesity management, our results suggest that fasting insulin and HOMA-IR values may be more clinically useful than CGM data alone." (PMID 36570168, 2022). "Markers of inflammation such as interleukin-1 beta (IL-1β), tumor necrosis alpha (TNF-α), monocyte chemoattractant protein-1 (MCP-1 or CCl-2), and interleukin 6 (IL-6), and markers related to obesity such as leptin and insulin were measured systemically in the blood." (PMID 36387539, 2022). "However, the investigation of phosphate derived from different sources on other MetS components including obesity, blood sugar, insulin, and lipid metabolism is limited, hence serving as the potential research gap to be filled by researchers." (PMID 36364791, 2022). "We first identified several obesity-related phenotypes, including BMI, triglycerides, fasting insulin and T2D, that might play a mediating role linking television watching with COVID-19 incidence." (PMID 35562752, 2022). "However, little is known about the effects of HM-chromanone on insulin resistance by FFAs released in obesity in skeletal muscle cells." (PMID 36145191, 2022). "The only effect of IN insulin was improved accuracy for selection of self-referent positive adjectives and rejection of negative adjectives and slower RT on the n-back task for women with obesity." (PMID 35397638, 2022). "Therefore, it can be said that L-carnitine should be consumed at a dose of more than 2 g/day for more than 12 weeks and often in individuals with obesity to have significant effects on insulin and HOMA-IR levels." (PMID 36704801, 2022). "The results suggest that polysulfides may normalize insulin sensitivity, at least in the adipose tissue, in obesity/metabolic syndrome." (PMID 35625574, 2022).
Obesity (continued). "Therefore, IR in SM importantly impacts blood glucose levels with consequences of altered insulin signaling for the whole body and is considered an important metabolic alteration related to obesity, which precedes T2D development." (PMID 36275635, 2022). "Insulin has been known to promote obesity by stimulating lipogenesis and inhibiting lipolysis." (PMID 35267892, 2022). "In experimental animals, obesity could be obtained using protamine zinc injections, a form of insulin that produced sustained decreases in blood glucose." (PMID 35662925, 2022). "The recent obesity development theory is explained by the “carbohydrate-insulin model” (CIM) based on the hormonal response to highly processed carbohydrates rather than the “energy balance model” (EBM) theory, which posits that obesity occurs because energy intake is less than consumption." (PMID 36615686, 2022). "In conclusion, GP always improves insulin sensitivity in this animal model of obesity, while the different compositions of GP modified by DIC may be associated with other cardiometabolic parameters." (PMID 36360149, 2022). "The higher need of pharmacotherapy in patients with obesity may be explained by impaired insulin action, which is often prevalent already before conception." (PMID 35663318, 2022). "Adipose tissues may play an important role in connecting ceramide metabolism, insulin resistance, and inflammation in diet-induced obesity in humans, as well as in intensively fed bulls exposed to a chronic nutrient surplus." (PMID 36003642, 2022). "Studies have shown that the metabolic regulation signaling pathway of insulin in obesity and T2DM is blocked; however, the signaling pathway that promotes proliferation is not blocked, which may lead to atherosclerosis and various microvascular complications." (PMID 35957821, 2022). "Fibrillation of the Drosophila heart may result from lipotoxic damage related to the insulin-TOR signal, which is moderate reduction in insulin-TOR signaling prevents HFD-induced obesity and cardiac dysfunction." (PMID 35657779, 2022). "Notably, we observed simultaneous anti-cancer effects with improvements in liver pathology and insulin sensitivity in our HFD/obesity-driven TRAMP model following Camkk2 ablation." (PMID 35741020, 2022). "Moreover, glucose regulates the transcription of several genes commonly regulated by insulin and fatty acids in adipose tissues, several of them are involved in the regulation of fat mass and involved in obesity." (PMID 35946137, 2022). "Such fiber-type differences have been previously correlated with decreased insulin sensitivity and could influence the difference in obesity and T2D rates between these two races." (PMID 35740478, 2022). "In addition, obesity can alter the central response to hormonal and nutrient signals and alter peripheral insulin sensitivity." (PMID 35725477, 2022). "For example, we have already discussed that the increase in irisin levels during obesity could play a role in β-cell compensatory insulin hypersecretion (Section 3.2)." (PMID 35628332, 2022). "We observed that seabuckthorn powder reversed HFD-induced obesity, improved systemic insulin sensitivity, and promoted thermogenic program in BAT and WAT, which might be attributed to the activation of the AMPK/SIRT1 pathway." (PMID 35889860, 2022). "It is known that this protein may contribute to impaired insulin sensitivity and AT dysfunction in obesity." (PMID 36142750, 2022). "Indeed, VAT is more metabolically active, has higher free fatty acids (FFAs) and glucose uptake, is less insulin sensitive, and therefore is thought to be more deleterious in the development of obesity‐related metabolic complications." (PMID 34985174, 2022). "In addition, results from studies conducted in mice suggest that obesity results in ultrastructural alterations to the muscle capillary endothelium which delay endothelial insulin transport." (PMID 35054781, 2022).